YIPF1 (Yip1 domain family member 1)
Synonyms: DJ167A19.1; FinGER1; Yip5a; YIPFbeta3A
Tractability: Antibody: its Gene Ontology location is reachable by antibodies, with high confidence; UniProt predicts a signal peptide or a membrane-spanning region. PROTAC: ubiquitination databases record sites on it; its protein half-life has been measured.
Gene: Protein-coding gene on chromosome 1 (53,847,531 to 53,890,683, reverse strand). Ensembl gene ENSG00000058799.
Subcellular location: Golgi apparatus, cis-Golgi network membrane; Golgi apparatus, trans-Golgi network membrane; Late endosome membrane
Subcellular location (Human Protein Atlas): Golgi apparatus; Nucleoplasm; Plasma membrane
Gene Ontology:
Molecular function: protein binding; small GTPase binding
Biological process: vesicle-mediated transport
Cellular component: Golgi apparatus; Golgi medial cisterna; Golgi trans cisterna; late endosome membrane; trans-Golgi network; transport vesicle; endomembrane system; membrane
Genetic constraint (gnomAD): Loss-of-function variants: 22 observed, 36.9 expected, observed/expected ratio (o/e) 0.6, 90% interval 0.43 to 0.85. The upper end of that interval is the gene's LOEUF score, 0.85, which puts it in group 3 of 6, group 1 being the genes least tolerant of losing a copy. Missense variants: 354 observed, 383.5 expected, observed/expected ratio (o/e) 0.92, 90% interval 0.85 to 1.01. Synonymous variants: 128 observed, 137.25 expected, observed/expected ratio (o/e) 0.93, 90% interval 0.81 to 1.08.
Homologues: Orthologues: chimpanzee YIPF1 (98% identical), guinea pig YIPF1 (92% identical), rabbit YIPF1 (91% identical), pig YIPF1 (88% identical), mouse Yipf1 (88% identical), rat Yipf1 (82% identical), tropical clawed frog yipf1 (64% identical), zebrafish yipf1 (55% identical), Drosophila melanogaster CG4645 (36% identical), Caenorhabditis elegans Y25C1A.7 (34% identical). Paralogues in human: YIPF2 (49% identical).
Diseases named in the same sentence as YIPF1 in open-access papers:
YIPF1 is named in the same sentence as 4 diseases in open-access papers, as found by Europe PMC text mining. Sharing a sentence is not in itself a finding about the gene and the disease. The quoted sentences say what the papers report.
liver cancer (1 paper, 2024). An epithelial or non-epithelial malignant neoplasm that arises from the liver. "rs2294510 is also an eQTL for the expression of the gene YIPF1 in testis, and interestingly higher expression of this protein was reported as a poor prognosis marker in liver cancer." (PMID 38365720, 2024).
YIPF1 also shares sentences with these, for which no sentence is quoted: cancer (1 paper); depression (1); schizophrenia (1).